PTTG1 (PTTG1 regulator of sister chromatid separation, securin)
Diseases named in the same sentence as PTTG1 in open-access papers (continued):
Sharing a sentence is not in itself a finding about the gene and the disease.
cancer (continued). "In fact, PTTG1 overexpression is reported in many cancer types, such as pituitary, thyroid, brain, and breast." (PMID 33430117, 2021). "Evidence shows that it is overexpressed in many carcinomas and regulates the expression of tumor oncogene human pituitary tumor transforming gene-1 (PTTG1) to enhance the migration and invasion capabilities of cancer cells." (PMID 34408975, 2021). "PTTG1 contributes to different cancer-promoting pathways that can increase cell growth through a nuclear exclusion of p27." (PMID 34131308, 2021). "Pituitary tumor-transforming gene 1 (PTTG1) is a recently identified oncogene involved in the progression of malignant tumors, and the expression of the PTTG1 oncogene has been confirmed to be related to progression and prognosis of ccRCC patients." (PMID 33686949, 2021). "PTTG1 has been found overexpressed in many types of cancer cells, including the hepatoma cell line HepG2." (PMID 34603388, 2021). "The expression of PTTG1 was more evenly distributed in immune cells, while carcinoma cells showed moderately high levels of PTTG1." (PMID 34726341, 2021). "Several genes, including CCNB1, CDC20, CDC6, PLK1, and PTTG1, had multiple roles as core essential genes, oncogenes, and roles as hallmarks of cancer and in KEGG pathways." (PMID 32040444, 2020). "We used seven data sets, including six GeneChips (GPL570, GPL571, GSE23400, GSE32424, GSE45168, and GSE70409), and RNA-seq data (2,307 cases in total, with 620 cases of ESCC and 1,687 non-cancer cases) to investigate the expression of PTTG1 in ESCC." (PMID 33552118, 2020). "In the same group of cancers, the highest fold change of PTTG1 was obtained for LIHC (4.42) and the lowest for SKCM (0.89) and THCA (0.89)." (PMID 32824814, 2020). "Previous research also demonstrated that PTTG family members play crucial roles in cancer metabolism, as microRNA (miR)-186 targets PTTG1 to regulate malignant phenotypes and aerobic glycolysis." (PMID 33173433, 2020). "Particularly, identification of inhibitors of PTTG1 expression would provide novel therapeutic approaches for suppressing cancer metastasis." (PMID 33250768, 2020). "Previous studies have demonstrated that PTTG1 promotes cancer cell proliferation, migration, and invasion." (PMID 32272902, 2020). "In the same group of cancers, the highest fold change of PTTG1 was observed for LUAD (1.63), while the lowest for READ (1.17)." (PMID 32824814, 2020). "In the same group of cancers, the highest fold change of PTTG1 was observed for CESC (3.14) and the lowest for HNSC (1.18)." (PMID 32824814, 2020). "Our findings suggest that the three cancer-associated gene expression regulators, PA2G4, PTTG1 and YB-1, play important roles in progression of HCC." (PMID 33379356, 2020). "Pituitary tumour transforming gene 1 (PTTG1) is over-expressed in a vast array of malignancies including pituitary, thyroid, colorectal and lung cancer." (PMID 30822312, 2019). "Previous data reported that altered levels of Pituitary-tumor-transforming-gene 1 (PTTG1) are expressed in pre-cancer lesions, suggesting that PTTG1 has a role in human tumorigenesis." (PMID 31572301, 2019). "Our current findings provide a novel mechanism for the chemotherapeutic action of luteolin in various cancer cells with PTTG1 overexpression." (PMID 29649138, 2018). "PTTG1 has been reported to regulate the effectiveness of anti-cancer drugs in some cancer cell lines." (PMID 29649138, 2018). "Differential expression of the PTTG1 protein is known to regulate cancer cell progression and the chemotherapeutic effects of anti-cancer agents." (PMID 29649138, 2018). "In hematological malignancies, PTTG1 oncoprotein is overexpressed and has been reported to promote cell proliferation, regulate the cell cycle, and modulate apoptosis in cancer cells." (PMID 29649138, 2018). "Tuning of PTTG1 gene expression by using anti-sense siRNA is considered to be an effective modality to reduce cancer aggressiveness." (PMID 29861465, 2018).
cancer (continued). "PTTG1 can also affect the invasive capacity of cancer cells through positive modulation of several matrix metalloproteinases (MMPs)." (PMID 29371923, 2017). "A number of experimental evidences also support a role of PTTG1 in the regulation of cancer cell response to therapy." (PMID 29371923, 2017). "Recently, pituitary tumor transforming gene 1 (PTTG1) was shown to be involved in invasion and proliferation of cancer." (PMID 26900962, 2016). "These evidence that PTTG1 regulates trophoblast invasion in a manner similar to the control of cancer metastasis." (PMID 26900962, 2016). "Over-expression of PTTG1 promotes dysregulated chromosome segregation resulting in aneuploidy in human cancer cell lines." (PMID 26445238, 2015). "Abnormal transcription and expression of PTTG1 and FoxM1 are involved in cancer progression and metastasis." (PMID 26264222, 2015). "In the ongoing search for molecular points of therapeutic intervention for various malignancies, both PTTG1 and FoxM1 have been considered as promising and attractive targets for cancer therapy." (PMID 26264222, 2015). "Pituitary Tumor-Transforming gene 1 (PTTG1), an oncogenic transcription factor, is abundantly expressed in various human cancers and hematopoietic malignancies." (PMID 23977008, 2013). "Heterogeneity of Forkhead box M1 (FOXM1), matrix metallopeptidase 9 (MMP9), and pituitary tumor-transforming 1 (PTTG1) were involved in cancer invasion and migration." (PMID 23577100, 2013). "Given the proximity of PTTG1 to pre-miR-146a and its postulated role in cancers, we extended our analyses to this gene." (PMID 24145614, 2013). "In HCT116 PTTG1−/− cells, knock down of p21 levels reduced the number of senescent cells, suggesting that p21 is critical for the enhanced senescence observed in HCT116 PTTG1−/− cancer cells." (PMID 21858218, 2011). "In conclusion, these results demonstrate that PTTG1 regulates drug-induced senescence, providing new insights for the role of PTTG1 in determining cancer cell responses to anti-neoplastic treatments." (PMID 21858218, 2011). "Since PTTG1 was isolated and characterized, there have been nearly 100 articles published on the role of PTTG1 in various cancers." (PMID 19014669, 2008). "Overexpression of PTTG1 in cancer cells supports the argument that PTTG1 is actively involved in cell proliferation as the cancer cell has the highest cell proliferation capacity." (PMID 19014669, 2008). "In the cells where both of the apoptotic pathways fail, PTTG1 induces these cells to undergo aneuploidy, which eventually results in cancer." (PMID 19014669, 2008). "While promising, several challenges remain in targeting PTTG1 in cancer therapy." (PMID 40072059, 2025). "Several molecular pathways are likely involved in the regulation of cancer stem cells (CSCs) via Ras-associated C3 botulinum toxin substrate 2, RAC2, and pituitary tumor-transforming gene 1 product, PTTG1, given their roles in cellular signaling, survival, proliferation, and metastasis." (PMID 40072059, 2025). "PTTG2 and PTTG3P, being homologous to PTTG1, have roles not fully elucidated, but their confirmed association with human cancer development is acknowledged." (PMID 40877987, 2025). "Then, we analyzed the expression of PTTG1 in TCGA pan-cancer." (PMID 39144144, 2024). "Additionally, PTTG1 is found in various cancer types, including HCC, where its high expression is associated with poor prognosis." (PMID 39006628, 2024). "Another study revealed that PRR11 could promote cell proliferation by regulating PTTG1 through interaction with the transcription factor E2F1 in the pan-cancer setting." (PMID 38427643, 2024). "Moreover, PTTG1 can increase the expression of matrix metalloproteinases that degrades the extracellular matrix and allows cancer cells to invade surrounding tissues." (PMID 38465336, 2024).
cancer (continued). "Finally, GSEA showed that many immune-related pathways, such as the T-cell receptor signaling pathway and the chemokine signaling pathway, were enriched in patients with low PTTG1 expression in most of the cancer types." (PMID 39144144, 2024). "PTTG1 is a well-known oncogene involved in the progression of several cancer histotypes." (PMID 38069214, 2023). "Finally, the experiment verified that the model genes LTB and PTTG1 were relatively highly expressed in cancer tissues, while PTPRC was relatively highly expressed in paracancerous tissues." (PMID 37671160, 2023). "In addition, a GEO data set (GSE48075) verified that high expression of PRR11 and PTTG1 was significantly related to the poor prognosis of cancer patients." (PMID 36060253, 2022). "But, however, the analysis between expression of PTTG1 and human pan-cancer was still poor." (PMID 35281830, 2022). "The present study shows the results of the comprehensive pan-cancer analysis data of PTTG1." (PMID 35281830, 2022). "Additionally, the involvement of PTTG1 in the proliferation and invasive potential of different human cancer cells has also been suggested through the regulation of the TGF-β1 signaling pathway." (PMID 35684123, 2022). "Moreover, the novel role of PRR11 in modulating PTTG1 expression showing its positive function in the cell cycle will likely encourage people to study the functions of PRR11 in the development of pan-cancer." (PMID 36060253, 2022). "Indeed, we previously demonstrated that, in the periphery of seminoma tumors, PTTG1 is localized in the nucleus, suggesting that the more invasion-prone cancer area requires nuclear localization of the securin." (PMID 36230799, 2022). "In summary, it is suggested that PTTG1 mRNA over-expression may operate as a cancer-promoting factor and could have the potential to be a predictor of poor prognosis in BLCA." (PMID 35768832, 2022). "The analysis of gene alteration, PTTG1 expression, prognostic function, and PTTG1-related immune analysis in 33 types of tumors was performed based on various databases such as The Cancer Genome Atlas database, the Genotype-Tissue Expression database, and the Human Protein Atlas database." (PMID 35281830, 2022). "However, all previous reports on PTTG1 expression by targeting miR-186 and miR-655 were insufficient to clearly explain the mechanisms of cancer invasion and metastasis." (PMID 33498448, 2021). "PTTG1 is widely known as an oncogene involved in the development of several cancers." (PMID 33430117, 2021). "Since several groups reported that PTTG1 promoted the invasion ability in different types of cancer cells, we investigated whether PTTG1 regulated the invasion ability of YD-10B and YD-15 cells using a Transwell chamber assay." (PMID 33498448, 2021). "Finally, we revealed that high levels of PTTG1 and PTTG3 transcription predicted poor survival, which provided useful insights into prospective research of cancer associated with the PTTG family." (PMID 33173433, 2020). "Since small GTPases are critically involved in organizing the actin cytoskeleton, it would be interesting to determine whether disruption of actin cytoskeleton, which is a promising and intriguing anticancer strategy, inhibits PTTG1 expression in cancer cells." (PMID 33250768, 2020). "It will be interesting to investigate whether PTTG1 directly targets the p63 promoter and how PTTG1 interacts with p63 in the process of cancer drug treatment." (PMID 29649138, 2018). "It seems that the relationship between PTTG3P and PTTG1 varies in different cancers." (PMID 29803224, 2018). "Luteolin is beneficial for the treatment of cancer cells with highly expressed PTTG1 oncoprotein." (PMID 29649138, 2018). "Recent studies have shown that PTTG1 could participate in cancer invasion and metastasis via promoting EMT." (PMID 29190924, 2017). "The mechanisms underlying the regulation and the downstream signaling pathway of PTTG1 in various cancer cells remain largely unknown." (PMID 27893422, 2017).
cancer (continued). "KLF6 has been reported to upregulate p21 and ATF3, but suppress PTTG1 expression in cancer cells." (PMID 28572744, 2017). "Recent research indicated that PTTG1 regulates cancer cell growth responses to treatments." (PMID 21858218, 2011). "As senescence also determines cancer therapy outcomes, we examined whether PTTG1 regulates drug-induced cellular senescence." (PMID 21858218, 2011). "Therefore, detailed studies on PTTG1 in angiogenesis are essential for developing a stage-specific as well as a targeted cancer therapy." (PMID 19014669, 2008). "In this section, we describe the possibilities of exploring PTTG1 for targeted cancer therapy." (PMID 19014669, 2008). "Our findings from the methylation analysis indicated that PTTG1, PTTG2, and PTTG3P exhibit hypomethylation in LUAD cells, which may underlie their increased expression, emphasizing the role of epigenetic modifications in cancer development." (PMID 40877987, 2025). "For PTTG1, there was a significant increase in expression from Stage I to Stage IV (F value = 5.22, p = 0.0015), suggesting that PTTG1 expression may correlate with cancer stage progression." (PMID 40877987, 2025). "Finally, PTTG1 was analyzed at the pan-cancer level by the pan-TCGA cohort." (PMID 39144144, 2024). "Additionally, HDAC2, MCM7, and PTTG1 have also shown potential for treating cancers." (PMID 38001498, 2023). "Finally, PTTG1 is considered an oncogene and its overexpression has been related to cell growth, epithelial mesenchymal transition, angiogenesis, invasion, and metastasis in cancer." (PMID 35805898, 2022). "Notably, PRR11 may play an oncogenic role in pan-cancer progression by regulating the expression of PTTG1 to involve in the cell cycle." (PMID 36060253, 2022). "Therefore, PTTG1 expression was at the same level among different cancer categories, but PTTG1 may be overexpressed in some normal tissues or cells compared to other normal tissues." (PMID 35281830, 2022). "Recently, an overexpression of the pituitary tumor-transforming gene 1 (PTTG1) and its transcriptional target matrix-metalloproteinase-2 have been reported in TCAM-2 and SEM-1 cells, suggesting that PTTG1 might play a role in the invasiveness and metastasis of cancer cells." (PMID 35684123, 2022). "Therefore, we found that PRR11 served as an oncogene in pan-cancer and could influence the cell cycle progression through regulating the expression of PTTG1 by interacting with the transcription factor E2F1." (PMID 36060253, 2022). "However, the expression of PTTG1 showed low cancer specificity in the RNA cancer category." (PMID 35281830, 2022). "PRR11 silencing could suppress the expression level of PTTG1 in pan-cancer." (PMID 36060253, 2022). "However, the anti-cancer effectiveness of luteolin in cancer cells with differentially expressed PTTG1 remains unclear." (PMID 29649138, 2018). "Together, these findings suggest that these PTTG1-targeting miRNAs are important players in the regulation of pituitary tumorigenesis and that these miRNAs may serve as valuable therapeutic targets for cancer treatment." (PMID 26320179, 2015). "Therefore, down-regulation of PTTG1 or inactivation of its tumorgenic function in cancer may become an important target in developing new cancer therapies." (PMID 19014669, 2008). "PTTG1 is capable of inhibiting TGFβ1/SMAD3 signaling and, in turn, suppressing apoptosis and promoting cancer growth." (PMID 40072059, 2025). "Both RAC2 and PTTG1 contribute to the activation of the NF-κB and PI3K/AKT signaling pathways, which are essential for cancer cell survival, invasion, and therapy resistance." (PMID 40072059, 2025). "CDC20, KIF20A and PTTG1 combined knockdown inhibited cell viability and DNA replication in both LGG (LN229/HS683) and GBM (U87MG/U343) cancer cell lines." (PMID 40047299, 2025). "PTTG1 promotes angiogenesis by activating HIF-1α signaling, maintaining cancer stem cell (CSC) survival, and regulating vascular niche formation and metastasis." (PMID 41312363, 2025).
cancer (continued). "This article aims to describe the molecular pathways involved in the proliferation, invasiveness, and drug response of cancer cells through RAC2 and PTTG1, aiming to clarify their respective roles in neoplastic process dependencies." (PMID 40072059, 2025). "RAC2 and PTTG1 play significant roles in promoting EMT, which gives cancer cells stem-like properties and enhances their metastatic potential." (PMID 40072059, 2025). "Overall, this study highlights the significance of PTTG1 and PTTG2 in LUAD and presents a strong case for their potential as biomarkers and therapeutic targets, offering valuable directions for future cancer research and treatment development." (PMID 40877987, 2025). "Subsequently, a CAF subpopulation which highly expressed cycle-related genes (CENPF, NUSAP1, and PTTG1) was annotated as proliferative CAF (prolif CAF), consistent with previous pan-cancer research." (PMID 39703515, 2024). "SNHG15, hsa.miR.130a.3p, PTTG1, INSR and HMMR were described in a ccRCC environment, exhibiting the higher expression that induces metastasis and promotes cancer development." (PMID 38673800, 2024). "For example, PTTG1 can activate the phosphatidylinositol 3-kinase (PI3K)/protein kinase B (AKT) signaling pathway, which is crucial for cancer cell migration and invasion." (PMID 38465336, 2024). "It was found that PTTG1 involved in the cell cycle was upregulated in 10 out of 11 cancers and downregulated in NCI-H460 and BxPC3 cancer cell lines with interfering PRR11." (PMID 36060253, 2022). "Thus, PRR11 silencing in pan-cancers could suppress the expression level of PTTG1." (PMID 36060253, 2022). "Interestingly, the expression of PTTG1 was lower in cancer than corresponding normal tissue in LAML and TGCT, which might mean the PTTG1 would be a “double-edged sword” for the PTTG1 was oncogene in most of tumors but also tumor suppressor gene in tumors such as LAML and TGCT." (PMID 35281830, 2022). "Moreover, we showed that the PTTG1 positive cell population in peripheral areas was characterized as octamer-binding transcription factor 4 (OCT4) and transcription factor Krüppel-like factor 4 (KLF4) positive, proteins associated with cancer stem cell self-renewal and invasiveness." (PMID 33430117, 2021). "In particular, five prognostic gene links for kidney renal papillary cell carcinoma tended to condense around cancer gene ESPL1, and the transcriptional synchrony between ESPL1 and PTTG1 tended to be elevated in patients of adverse prognosis." (PMID 34856998, 2021). "In addition, IL-6/JAK/STAT3 signaling could induce “pituitary tumor transforming gene 1” (PTTG1) overexpression with subsequent induction of epithelial-mesenchymal transition, increasing the cancer stem cell population in LNCaP androgen-dependent PC cell lines." (PMID 34830209, 2021). "Liver hepatocellular carcinoma patients who were with advanced cancer stages inclined to have the higher mRNA expression levels of CDK1, HMMR, PTTG1, and TTK." (PMID 34187556, 2021). "The expression levels of UBE2S, PTTG1, and CDC20 were significantly higher in most cancer tissues than in normal tissues." (PMID 34726341, 2021). "Pituitary tumor transforming genes (PTTG1, PTTG2, and PTTG3P) play key roles in the pathogenesis and development of human cancers." (PMID 33845847, 2021). "Among all PTTG members, PTTG1 and PTTG3 were especially distinctively highly expressed in cancers compared to normal tissues, implying their specific roles in cancer progression." (PMID 33173433, 2020).